TRIM21 (tripartite motif containing 21)
Diseases named in the same sentence as TRIM21 in open-access papers (continued):
Sharing a sentence is not in itself a finding about the gene and the disease.
cancer (continued). "Thus, future perspectives include the development of TRIM21-based therapeutic strategy and their effective delivery into cancer cells." (PMID 40735642, 2025). "TRIM21 has been widely discussed in cancer progression in many studies." (PMID 38720056, 2025). "Mechanisms of these seemingly contradictory roles of TRIM21 in cancer remain elusive; however, we could partially explain the opposite results." (PMID 39016065, 2024). "We examined TRIM21 as a potential target for cancer therapy." (PMID 37771771, 2023). "Given that depletion of TRIM21 can potentiate radiation-induced antitumour immunity, either genetic deletion or pharmacological inhibition of TRIM21 may be a promising therapeutic strategy for cancer." (PMID 36797289, 2023). "TRIM21-targeted agonists and inhibitors have great potential in cancer treatment." (PMID 36694250, 2023). "Taken together, the research of TRIM21 may provide new ideas for the diagnosis and treatment of malignant tumors, and the research as a targeted treatment site of malignant tumors has achieved initial success." (PMID 37335642, 2023). "Currently, the precise role and mechanism of TRIM21 in cancer remain elusive." (PMID 36749630, 2023). "The dysregulation of TRIM21 expression contributes to the pathogenesis of various human cancers." (PMID 37249651, 2023). "The role of TRIM21 as a prognostic biomarker has previously been analyzed in other cancer entities." (PMID 36982215, 2023). "Emerging evidence has suggested that TRIM21 is involved in cancer." (PMID 36749630, 2023). "TRIM21 overexpression caused a significant increase in the ubiquitination of IDO1, whereas ubiquitination of IDO1 was noted to be reduced in TRIM21-depleted cancer cells." (PMID 37830596, 2023). "Emerging evidence has shown that TRIM21 plays dual roles in cancer." (PMID 37587773, 2023). "However, further studies are required to reveal the precise regulation of TRIM21 levels and activity in normal and cancer cells and tissues." (PMID 36749630, 2023). "Therefore, our understanding of TRIM21 in cancer should not only be limited to its E3 ubiquitin ligase function but also focus on its substrate function." (PMID 37904651, 2023). "In light of this, the prognostic value of TRIM21 may vary in different cancers because of different mechanisms of TRIM21." (PMID 37335642, 2023). "Moreover, the overexpression of TRIM21 or FSP1 promoted cancer cell resistance to ferroptosis, and co‐overexpression had an additive effect." (PMID 37587773, 2023). "Moreover, TRIM21 is highly expressed in multiple gastrointestinal (GI) tumors, and its expression is further stimulated upon ferroptosis induction in cancer cells and the KPC mouse model." (PMID 37587773, 2023). "The Development of agonists or inhibitors targeting TRIM21 has huge potential for cancer therapy." (PMID 36694250, 2023). "Besides, the role of TRIM21 in various cancers has been observed in many studies, but the conclusions are inconsistent." (PMID 37335642, 2023). "Our findings imply that TRIM21 catalytic activity could be a potential target for anti-cancer drug development and therapy." (PMID 35048968, 2022). "More and more studies have focused on the regulatory role of TRIM21 in cancer metabolism." (PMID 36159815, 2022). "Expression of the E3 ligase TRIM21 is increased in a broad spectrum of cancers; however, the functionally relevant molecular pathway targeted by TRIM21 overexpression remains largely unknown." (PMID 35048968, 2022). "TRIM21 is involved in innate immunity and cancer progression." (PMID 35024438, 2022). "Previous studies have found that TRIM21 is upregulated in cancers." (PMID 35048968, 2022). "Multiple key molecules involved in cancer metabolism, immunity, especially in inflammation-associated tumorigenesis and cancer treatment have been identified as ubiquitination substrates of TRIM21, unfortunately without a systematic review of these topics yet." (PMID 36159815, 2022).
cancer (continued). "In this study, we demonstrate that in response to replication stress, over-expression of TRIM21 in cancer cells ubiquitinates CLASPIN with K63-linkage type, which counteracts its K6-linked ubiquitination, thus compromising CHK1 activation and stability of stalled replication forks." (PMID 35048968, 2022). "A recent study found that TRIM21 was decreased in CRC and ulcerative colitis (UC)-associated cancer and negatively regulated intestinal epithelial carcinogenesis by modulating epithelial cancer cell proliferation, adhesion, tissue remodeling, angiogenesis, and proinflammatory responses." (PMID 36261847, 2022). "This indicates that TRIM21 may act both in cancer proliferation and in cell apoptosis, an ambivalent role that still deserves further investigations." (PMID 34439361, 2021). "Our present data also suggest that cancer with low TRIM21 expression could be more resistant to TRAIL-induced necroptosis, a backup cell death pathway that can be triggered when apoptosis cannot occur." (PMID 33937329, 2021). "TRIM21 may enhance cancer proliferation, or alternatively, it may increase the ubiquitination of many cancer-triggering proteins, determining their proteasomal-mediated degradation." (PMID 34439361, 2021). "Besides a role for TRIM21 in many cellular processes such as cell proliferation, apoptosis, and innate and adaptive immunity, several studies have shown that TRIM21 is involved in the progression of human cancers." (PMID 33937329, 2021). "ANO1 downregulation, on the other hand, allows p27Kip1 accumulation to occur in the absence of TRIM21, thereby causing a p27Kip1-dependent G1 arrest in a similar manner as previously observed in the case of HeLa cancer cells." (PMID 33803266, 2021). "Nevertheless, TRIM21 SNPs can promote OSCC progression while the cancer is occurred." (PMID 34220328, 2021). "Tripartite motif 21 (TRIM21) has been reported to play an important role in different cancer types." (PMID 34220328, 2021). "The expression of TRIM21 is closely related to the response to cancer and cell apoptosis." (PMID 33194761, 2020). "Therefore, it is of interest that a regulator such as TRIM21 has been discovered as a new component of the extensively studied DNA damage response pathway, providing new targets for therapeutic intervention in cancer." (PMID 32678213, 2020). "Importantly, a strong negative correlation was also found between PI3K pathway activity and TRIM21 expression in several human cancers (Spearman’s rank correlation rho was −0.63 and −0.61, respectively, with a p value lower than 0.01)." (PMID 32312982, 2020). "As TRIM21 is a RING-finger domain-containing ubiquitin E3 ligase that plays an important role in cancer progression, we hypothesised that TRIM21 might be involved in the blockage of the ubiquitinated degradation of PHB1 by LPLUNC1." (PMID 30886235, 2019). "Moreover, TRIM21 exhibits a context-dependent dual role in cancer progression." (PMID 40735642, 2025). "However, recent research has also shed light on the role of TRIM21 in malignant tumors." (PMID 39890802, 2025). "Besides, TRIM21 could improve the toxicity of chemotherapeutic agents by regulating ferroptosis responsiveness in cancer." (PMID 40175350, 2025). "Notably, the role of TRIM21 varies across different cancers." (PMID 40265981, 2025). "In conclusion, TRIM21 may affect the prognosis of cancer in some extent." (PMID 37335642, 2023). "Hence, modulating the degradation process of BRCA1, as well as other vital proteins in cell activity by TRIM21, may be feasible for cancer treatment and needs to be more profoundly investigated." (PMID 37864041, 2023). "In addition, some studies have suggested that TRIM21 may play a role in the development and progression of certain diseases, including cancer." (PMID 37171396, 2023). "Importantly, TRIM21 has been extensively involved in cancer development." (PMID 37864041, 2023).
cancer (continued). "Moreover, it was revealed that TRIM21 is not only a target protein and possesses great potential as a therapeutic target for diverse types of cancer, but also may be a tool enzyme with promise from bench to bedside." (PMID 37864041, 2023). "Furthermore, TRIM21 knockdown partially reversed the cancer-promoting effects of MICALL2 in CRC cells, suggesting that TRIM21 may be a crucial regulatory molecule for MICALL-mediated oncogenic signaling in CRC." (PMID 36307841, 2022). "An instructive hint is that the role of TRIM21 in tumors is complex and depends on the cell type and the nature of the stimulatory signal, the expression level of TRIM21 in each cancer types may require more studies to focus on the upstream signal of TRIM21 and explain how TRIM21 is regulated." (PMID 36159815, 2022). "Furthermore, current studies mostly addressed cancer metabolism in vitro level, whether the effect of TRIM21 on metabolism can be replicated in vivo is of great significance." (PMID 36159815, 2022). "Therefore, we systematically outline the role and function of TRIM21 in cancer metabolism, immunity and cancer treatment, and discuss the possible function of TRIM21 in inflammation-associated tumorigenesis, hoping to shine a light on the great potential for targeting TRIM21 as a therapeutic target." (PMID 36159815, 2022). "Therefore, TRIM21 may act at multiple nodes to control normal cell metabolism and cancer metabolic reprogramming." (PMID 32312982, 2020). "Moreover, TRIM21 is also thought to play a role in different human cancers." (PMID 32678213, 2020). "However, the precise role and intricate mechanisms of TRIM21 in cancers remain unclear." (PMID 40605974, 2025). "To further elucidate the impact of the STAMBPL1/TRIM21/AXL axis on metastasis in vivo, we constructed the tail‐vein cancer metastasis model using 786‐O sublines in BALB/c nude mice." (PMID 39527690, 2025). "Modulation of cancer immunity by TRIM members of the RING ligase family: TRIM E3 ligases, including TRIM7, TRIM21, and TRIM32, execute a proper immune response against pathogens." (PMID 39851497, 2025). "Tripartite motif-containing protein 21 (TRIM21) is well known to be involved in inflammation, autoimmunity and cancer, mainly via its E3 ubiquitin ligase activity." (PMID 39103348, 2024). "MTA1 expression was positively correlated with cancer histological grade, whereas those of MTA3 and TRIM21 were the opposite." (PMID 39154024, 2024). "Thus, the levels of TRIM21 expression may vary in different types of malignant tumors." (PMID 38385081, 2024). "Based on these guidelines, TRIM21 and TRIM48 were identified as candidate cancer-relevant TRIM genes from our database screen." (PMID 37771771, 2023). "Taken altogether, we proposed a putative model in which HHT blocks the interaction between CDK2 and Cyclin A. This enhances interactions between CDK2 and Trim21, which recruits autophagic machinery to degrade CDK2 in cancer cells." (PMID 35595767, 2022). "To investigate the clinical impact of TRIM21 on HNSCC cancer progression, we used GEPIA to assess the relationship between cellular levels of TRIM21 mRNA and HNSCC patient outcomes." (PMID 34220328, 2021). "We characterised the role of CSN6 in regulating cancer stemness, which involves the TRIM21 E3 ubiquitin ligase, transcription factor POU class 2 homeobox 1 (OCT1) and cancer stem cell marker aldehyde dehydrogenase 1 A1 (ALDH1A1)." (PMID 32225170, 2020). "In validation of the relevance of our findings to human cancer, our Kaplan–Meier analysis indicated that CRC patients with High CSN6 and Low TRIM21 expression exhibit the poorest overall survival." (PMID 32225170, 2020).
cancer (continued). "We further demonstrated that CSN6 facilitates TRIM21 autoubiquitination at the K214 and K217 sites, thereby reducing ubiquitination and degradation of OCT1, a transcription factor for the cancer stemness marker ALDH1A1." (PMID 32225170, 2020). "PI3K/AKT signaling also plays a similar role in regulating TRIM21 expression and G6PD protein levels in human cancers." (PMID 32312982, 2020). "In line with this, both TRIM21 and endoglin appear to induce the epithelial–mesenchymal transition (EMT), a key process in cancer development." (PMID 31540324, 2019). "Furthermore, we intravenously injected engineered luciferase‐labeled 4T1 cells to assess the influence of TRIM21 and CCT6A on cancer metastasis." (PMID 39556022, 2024). "Tripartite Motif-Containing Protein 21 (TRIM21) is an important member of the TRIM family that contains a C-terminal PRYSPRY domain, and emerging evidence shows that TRIM21 plays dual roles in cancer." (PMID 39019859, 2024). "TRIM21 belongs to the TRIM family and contains a RING domain with E3 ubiquitin ligase activity, functioning as an essential regulator of immunity and cancer." (PMID 38092733, 2023). "Our findings provide new insight into the mechanism by which cancer cells upregulate TRIM21 to promote the function of FSP1 to prevent ferroptosis and may shed light on ferroptosis‐related cancer therapy." (PMID 37587773, 2023). "Furthermore, we evaluated the relationship between TRIM21 expression and ferroptosis in RSL3‐treated cancer cell lines and the KPC mouse model." (PMID 37587773, 2023). "A further 333 were excluded after screening the title and abstract, being studies not regarding cancers, studies performed on animals, review papers, or studies not evaluating the TRIM21 gene." (PMID 37335642, 2023). "Moreover, histochemical staining of TRIM21 and lipid metabolism-related markers in carcinoma and adjacent tissues from six RCC patients was performed to preliminarily explore the potential relevance of TRIM21 and SREBF1." (PMID 36694250, 2023). "Taken together, these data suggested that the PI3K/AKT pathway negatively regulates the expression of the E3 ligase TRIM21, which in turn controls the level and activity of the PPP rate-limiting enzyme G6PD via ubiquitin-mediated degradation in vivo and in human cancers." (PMID 32312982, 2020). "Together, our data demonstrate that CSN6-facilitated self-ubiquitination and subsequent degradation of TRIM21 alters cancer stemness and that overexpression of CSN6 in cancer leads to deregulation of the TRIM21–OCT1–ALDH1A1 axis, thereby promoting cancer stemness during tumorigenesis." (PMID 32225170, 2020). "The negative regulators in these crosstalk mechanisms, such as TRIM21 and PHLDA3 discovered in this study, may contribute to cancer development and treatment resistance." (PMID 32312982, 2020). "Thus, both OM subsets were similar with respect to the frequencies of antisynthetase autoantibodies (35% vs 28%, respectively), anti-Ro52/TRIM21 autoantibodies (30% vs 35%, respectively), and cancer (0% in each subset)." (PMID 25500701, 2014). "In summary, we performed mechanistic studies illustrating the role of CSN6-facilitated TRIM21 ubiquitination in enhancing ALDH1A1 expression via the OCT1 transcription factor, lending support to the means by which CSN6 activity can lead to the initiation of cancer stemness." (PMID 32225170, 2020). "A recent study showed that PI3K/AKT activation increased the half-life of the G6PD protein through the inhibition of TRIM21-mediated ubiquitination, and the TRIM21 level had a negative correlation with PI3K/AKT activity in many human cancers." (PMID 37802999, 2023).
infection (87 papers, 2010 to 2026). The state of being infected such as from the introduction of a foreign agent such as serum, vaccine, antigenic substance or organism. "Instead, vaccinated mice deficient in the intracellular Fc-receptor TRIM21 were unable to control the infection despite mounting robust CCHFV-specific immunity." (PMID 39455551, 2024). "Compared to the control group, the increase in ROS caused by DK/212 infection after interference with TRIM21 was significantly reduced at 24 and 36 h." (PMID 38542289, 2024). "Recently, a mutated anti-adenovirus IgG with increased affinity for TRIM21 was shown to enhance dendritic cell (DC) activation and cytokine secretion upon infection of DCs with mutant IgG complexed adenovirus." (PMID 32760166, 2020). "TRIM21 intercepts incoming antibody-coated pathogens during cellular infection and causes them to be degraded by the proteasome." (PMID 31613747, 2019). "Our findings show that TRIM21-deficient mice exhibit death at 7 days post-infection, placing TRIM21 into the category of these major intracellular acute phase mediators of Toxoplasma resistance." (PMID 28701773, 2017). "The parasite load assessed by in vivo imaging revealed the high susceptibility of TRIM21-deficient mice to Toxoplasma acute infection is accompanied with a higher parasite burden 5 days post-infection." (PMID 28701773, 2017). "Characterization of these variants during infection revealed that TRIM21-dependent neutralization and NFκB activation was largely unaffected by on-rate kinetics." (PMID 27881870, 2016). "Here we investigated the antigenic features associated with a potent TRIM21-dependent anti-human adenovirus 5 (Adv5) IgG1 antibody and determined the kinetic requirements for efficient stimulation of antiviral activity upon infection." (PMID 27881870, 2016). "The results showed that, compared to the control group, the down-regulation of antioxidant gene mRNA caused by DK/212 infection was inhibited after interference with the expression of the TRIM21 gene, and the protein level of NRF2, SLC7A11, and GPX4 was increased." (PMID 38542289, 2024). "Additionally, TRIM21-deficient mice that presented poor physical condition typical of infection with Toxoplasma exhibited higher tachyzoite parasite counts in their brains compared to healthy wild-type animals on day 7 post-infection." (PMID 28701773, 2017). "A single point mutation in IgG, H433A, has been demonstrated to prevent TRIM21 interaction and abolish its function: Antibodies with mutation H433A lose TRIM21 antiviral activity in vitro, in both cell lines and primary human macrophages, and in vivo in a mouse model of infection." (PMID 33258165, 2021). "We co-expressed TRIM21-HA and SQSTM1-FLAG in A549 cells and observed that DK/212 infection enhanced the interaction between TRIM21 and SQSTM1." (PMID 38542289, 2024). "An important question unanswered by our studies is how anti-NP antibodies and CCHFV NP enter the cell to interact with cytoplasmic TRIM21 and control the infection in vivo." (PMID 39455551, 2024). "In conclusion, our study demonstrates that vaccine or infection elicited NP-specific antibodies can protect through TRIM21 in vivo." (PMID 39455551, 2024). "Strikingly, despite mounting comparable antibody responses to WT mice, all repNP vaccinated TRIM21−/− mice succumbed to the infection with the same MTD as sham-vaccinated animals." (PMID 39455551, 2024). "For instance, in vitro and in vivo studies have shown that TRIM21 expression is upregulated during infection with the porcine reproductive and respiratory syndrome virus (PRRSV), significantly inhibiting the replication of this virus." (PMID 37446070, 2023). "Recombinant adenoviral TRIM21 (Ad-Trim21) infection of mice increased hepatic TRIM21 expression to levels similar as those observed in mice on HFD or NASH diets." (PMID 37937648, 2023).